THRAP3 (thyroid hormone receptor associated protein 3)
Diseases named in the same sentence as THRAP3 in open-access papers (continued):
Sharing a sentence is not in itself a finding about the gene and the disease.
cancer (continued). "In order to investigate the expression level, prognostic significance, molecular function, signaling pathways, and immune infiltration pattern of THRAP3 in 33 kinds of cancer, we conducted a systematic bioinformatics analysis and experimental validation in LUAD." (PMID 38333620, 2024). "In cancer cells, Thrap3 interacts with DEAD-box helicase 5 (DDX5) and localizes to R-loops." (PMID 34697388, 2021). "Moreover, THRAP3 expression significantly correlates with tumor stage and age in various cancers." (PMID 38333620, 2024). "However, the biological activities of THRAP3 in pan-cancer remain unexplored." (PMID 38333620, 2024). "Given that mutant THRAP3 was expressed in a wt THRAP3 background, in both of these assays, this data suggest that mutant THRAP3 functions in a dominant negative manor, thus abrogating normal cellular DNA repair capacity and potentially contributing to cancer development." (PMID 29112714, 2017). "Given the role of THRAP3/BCLAF1 in the regulation of DDR proteins, we hypothesized that some cancer-associated mutations within THRAP3, particularly those that result in loss of THRAP3 structure/function, may confer a DNA repair defect on cells harboring these mutations." (PMID 29112714, 2017). "Among these genes, seven proteins (MAP2K1, FERMT2, HMGB2, FAF2, STK26, THRAP3, and KRT15) showed significant differences between carcinoma and adjacent tissues (TCGA-HNSC database)." (PMID 39319867, 2025). "In 17 cancer types, THRAP3 expression has a negative connection with ImmuneScore." (PMID 38333620, 2024). "However, there is no comprehensive analysis of the biological role of THRAP3 expression in pan-cancer." (PMID 38333620, 2024).
tumor (7 papers, 2016 to 2024). "Based on the CCLE data, THRAP3 expression levels in distinct tumor cell lines were measured and ranked from high to low." (PMID 38333620, 2024). "Genes CBX3, RCC1, TMOD3, and NOA1 (Cluster A) and TOP1, PDCD5, and THRAP3 (Cluster B) were upregulated for both datasets in PCa tissue vs. normal gland or normal adjacent to tumor tissue." (PMID 32640729, 2020). "Furthermore, tumor patients with THRAP3 overexpression have less sensitivity to 8−Chloro−adenosine, Pralatrexate, Gemcitabine based on the drug sensitivity data." (PMID 38333620, 2024). "We analyzed the differential expression of THRAP3 at various stages for each tumor." (PMID 38333620, 2024). "Additionally, THRAP3 expression negatively correlates with myogenesis, xenobiotic metabolism, coagulation, pancreas-β cells in tumor patients with THRAP3 overexpression." (PMID 38333620, 2024). "In addition, phosphorylated THRAP3 is involved in tumor progression in the androgen-independent prostate." (PMID 38333620, 2024). "Thus, THRAP3 protein has the potential to act as a specific tumor biomarker." (PMID 38333620, 2024).
endocrine diseases (1 paper, 2021). "Circadian clock-independent AS events that play an important role in the homeostasis of the endocrine system, such as alternatively spliced Clock and Bmal1, are regulated by thyroid hormone receptor-associated protein 3 (THRAP3) and are closely associated with endocrine diseases including PTC." (PMID 34722250, 2021).
infection (1 paper, 2024). The state of being infected such as from the introduction of a foreign agent such as serum, vaccine, antigenic substance or organism. "Additionally, positive interactors of DCAF11 that were lost upon infection encompass splicing factors THRAP3 and SRSF5, the microtubule-associated protein MAP4, mitochondrial ribosomal protein MRPL12, and the TUFM mitochondrial translation elongation factor." (PMID 39383947, 2024).
metabolic disease (1 paper, 2023). A congenital disorder (due to inherited enzyme abnormality) or acquired (due to failure of a metabolically important organ) disorder resulting from an abnormal metabolic process. "Further studies should focus on the role of Thrap3 in other metabolic diseases and in understanding the underlying mechanisms." (PMID 37524868, 2023).
THRAP3 also shares sentences with these, for which no sentence is quoted: gastric adenocarcinoma (2 papers); acute promyelocytic leukemia (1); adrenocortical carcinoma (1); astrocytoma (1); colon adenocarcinoma (1); Fanconi Anaemia (1); glioma (1); head and neck squamous cell carcinoma (1); heart disease (1); heroin addiction (1); lung squamous cell carcinoma (1); mantle cell lymphoma (1); melanoma (1); nonalcoholic fatty liver disease (1); oligodendroglioma (1); osteosarcoma (1); ovarian serous cystadenocarcinoma (1); testicular germ cell tumor (1).